KDM6B (lysine demethylase 6B)
Diseases named in the same sentence as KDM6B in open-access papers (continued):
Sharing a sentence is not in itself a finding about the gene and the disease.
tumor (continued). "Given other published study suggesting that tumor stem cells are a subgroup of tumor cells that exhibit drug resistance and high metastatic potential, we wondered whether the key epigenetic enzyme KDM6B demethylating histone H3K27me3 is involved in the regulation of OS metastasis." (PMID 33664867, 2021). "On the other hand, in our study we observed that the expression of upstream signaling molecules such as VEGFA and FGF1 was also regulated by KDM6B, which may form a positive feedback loop, strengthening the inhibition of tumor progression after targeted blockade of KDM6B." (PMID 33664867, 2021). "Therefore, further work needs to be performed to fully understand whether KDM6B is tumor suppressive or tumor promoting." (PMID 30634491, 2019). "KDM6B may have both tumor suppressive and oncogenic activities in different cancer types." (PMID 28968467, 2017). "Our data showed that KDM6B overexpression significantly increased phosphorylated STAT3 levels in CRC cells and tumor tissues compared with the control group." (PMID 40959109, 2025). "Inflammatory cytokines such as TNF-α and IL-6 have been shown to upregulate histone demethylases, including Jmjd3 (KDM6B), which affects the expression of genes, leading to stem-like, therapy-resistant tumour phenotypes." (PMID 40647494, 2025). "Overexpression of KDM6B significantly suppressed the malignant phenotypes of CRC, including cell proliferation, migration, invasion, tumor growth and liver metastasis." (PMID 40959109, 2025). "EZH2 has been involved in the tumor progression mechanisms of a variety of cancer types, whereas KDM6A and KDM6B have been identified in numerous malignancies with either oncogenic or tumor suppressor roles." (PMID 41085408, 2025). "KDM6B overexpression suppressed CRC proliferation, tumor growth and liver metastasis, while enhancing CD8+ T cells infiltration, recruitment, and functional activation." (PMID 40959109, 2025). "Genetic and pharmacologic inhibition of KDM6A and KDM6B sensitized cisplatin-resistant and wild-type TGCT cells to cisplatin and produced dramatic synergistic tumor regression in animal models." (PMID 39482699, 2024). "KDM6B expression is induced by retinoic acid via HOXC9 and inhibits tumor cell growth by promoting cell differentiation." (PMID 39239542, 2024). "Genetic and pharmacologic inhibition of polycomb H3K27me3 demethylases KDM6A and KDM6B sensitized cisplatin-resistant and wild-type TGCT cells to cisplatin and produced dramatic synergistic tumor regression in animal models." (PMID 39483904, 2024). "Targeting KDM6B with GSK-J4 suppresses cell proliferation and colony formation in AML cell lines, as well as tumor development in an AML xenograft mice model by enriching the H3K27me3 repressive mark in HOX genes’ transcription start sites." (PMID 37218871, 2023). "KDM6B is upregulated in hepatocellular carcinoma and clear cell renal cell carcinoma, leading to SLUG overexpression and the promotion of tumor cell proliferation and metastasis." (PMID 36564369, 2022). "Compared with the normal group, the tumor group had higher expressions of MLPH, MISP, KDM6B, and FXYD3 genes." (PMID 35673567, 2022). "In contrast to KDM6B, which seems to activate oncogenic gene expression to support AML pathogenesis, KDM6A has recently been shown to play a tumour suppressor role in AML." (PMID 35915507, 2022). "KDM6B knockdown can inhibit the expression of the CCAAT-enhancer binding protein alpha (CEBPA) gene and enhance tumor progression of PC cells both in vitro and in vivo." (PMID 35296007, 2022). "The in vivo experiment showed KDM6B KD in the PC3 and C42B cell xenografts remarkably decreased the tumor growth velocity and volume." (PMID 33414463, 2021). "We have also discussed mutations in other isoforms such as the JARID1A, 1B, 1D of KDM5 subfamilies and the JMJD3/KDM6B of KDM6 subfamilies, which play opposing roles in tumor progression as oncogenes or tumor suppressors depending on the cancer cell type." (PMID 31221981, 2019).
tumor (continued). "For example, even if KDM6B was overexpressed in pancreatic ductile adenocarcinoma (PDAC) compared to normal tissue, its expression decreased with tumor grades." (PMID 34991274, 2018). "In contrast, KDM6B expression is significantly reduced in HPV+ cancers compared to HPV- tumors in both the HNSC and CESC tumor types." (PMID 29069809, 2017). "Therefore, the aim of this study was to investigate the role of KDM6B in CRC progression and its regulation of tumor immunity." (PMID 40959109, 2025). "Although we defined 260 and 49 EWSR1::FLI1-KDM6A and KDM6B direct targets, respectively, affecting oncogene reprogramming, the contribution of the two demethylases to tumor growth in an oncogene-independent manner should not be dismissed." (PMID 41085408, 2025). "Unlike JMJD2D, which contributes to tumor formation,JMJD3 (KDM6B)is closely associated with inflammation." (PMID 41152016, 2025). "High levels of KDM6B induce the expression of mesenchymal genes, such as Snail and Slug (Snail Family Transcriptional Repressor 2), which promote TGF-β-induced (Transforming Growth Factor Beta 1) EMT and tumor metastasis." (PMID 36233212, 2022). "Interestingly, we also observed that KDM6B upregulated in KIRC compared with the adjacent normal tissues, but the expression level gradually decreased as the tumor progressed." (PMID 35783266, 2022). "Moreover, KDM6B inhibit CXCL9 and CXCL10 expression in colon cancer and exerts an anti-tumor immune effects." (PMID 36713412, 2022). "KDM6B has been identified as a new therapeutic target in B-cell malignancies, and its selective inhibitor GSK-J4 has been shown to counteract cell proliferation in different tumor types such as AML, MM and DLBCL." (PMID 34200679, 2021). "Importantly, the knockdown of C/EBPβ rescued proliferation, tumor formation and G1-S conversion of KYSE150 cell overexpressed by KDM6B." (PMID 34001062, 2021). "To explore a possible role of KDM6B-mediated H3K27me3 demethylation in OS, we first compared the expression of histone demethylase KDM6B in 12 pairs of tumor tissues and their corresponding nontumor counterparts." (PMID 33664867, 2021). "Rationale: Differential activation of macrophages correlates closely with tumor progression, and the epigenetic factor lysine demethylase 6B (KDM6B, previously named JMJD3) mediates the regulation of macrophage polarization through an unknown mechanism." (PMID 34093857, 2021). "GSEA analysis revealed that this 37-gene signature was significantly associated with the GSK-J4 treatment, suggesting that KDM6B inhibition consequently downregulates the functions of PRC2, leading to the induction of tumor-suppressive program repressed by EZH2." (PMID 34893606, 2021). "If ablation of KDM6A or KDM6B increases cancer cell metastasis, GSK-J4 treatment might result in increased tumor growth instead." (PMID 34950587, 2021). "As a result, several hub DEFs with maximum intramodular connectivity were identified (e.g., SOX4, EGR1, LEF1, FOS, MITF, KLF4, TCF7, and KDM6B), which might involve CD248-mediated tumor-promoting regulation in CAFs." (PMID 34970489, 2021). "Strikingly, Kdm6b expression was selectively downregulated in sphere-forming cells compared to primary tumor cells, as no significant changes were observed in the expression levels of other demethylase genes examined." (PMID 30631055, 2019).
tumor (continued). "Knockdown of KDM6B/JMJD3 (H3K27me3 demethylase) reproduced the effects of low glutamine, suggesting that O2- and α-KG-dependent histone demethylases mediate signals from tumor microenvironments and metabolic status to chromatin." (PMID 31221981, 2019). "Indeed, both these enzymes have been involved in EMT and tumor aggressiveness in various cancer cell types, and this review will specifically focus on the roles of EZH2 and KDM6B on the epigenetic regulation of EMT." (PMID 34991274, 2018). "Furthermore, we have characterized the role of KDM6B and SIRT1 for the tumor inhibitory mechanism of ERβ in the presence of its selective agonist KB9520." (PMID 29422491, 2018). "Inhibition of the histone demethylases KDM6A and KDM6B by a pharmacological inhibitor, GSKJ4, increased global H3K27me3 in K27M-mutant brainstem gliomas, leading to reduced tumor growth, improved survival, and sensitized tumor cells to radiation therapy in preclinical models." (PMID 40556679, 2025). "Lysine-specific demethylase 6B (KDM6B), is a key histone demethylase in various normal and pathological processes such as inflammation, development, aging, and cancer.High levels of KDM6B have been confirmed to regulate tumor progression by mediating cell proliferation, migration, and senescence." (PMID 40832611, 2025). "The Jumonji domain-containing protein-3 (JMJD3), also known as lysine-specific demethylase 6B (KDM6B), is a histone demethylase that regulates the trimethylation of histone H3 on lysine 27 (H3K27me3), and it has been studied extensively in immune diseases, cancer, and tumor development." (PMID 35563264, 2022). "To investigate the effect of KDM6B on the migration ability of GC cells in vivo, we injected the cells that stably carry the construct, knockdown Lv-shKDM6B-MKN-45 or its negative control Lv-shNC-MKN-45 into nude mice via the tail vein to establish an in vivo tumor metastatic model." (PMID 36564369, 2022). "KDM6B mediates carcinogenic and anti-cancer signaling pathways by directing distinct transcription factors in a context-dependent manner, imposing wide-ranging effects on proliferation, apoptosis, migration, stem cell behavior, EMT, drug resistance and tumor microenvironment." (PMID 34950587, 2021). "Nevertheless, the loss of KDM6B resulted in TH2 and TH17 differentiation, indicating that the targeting of KDM6B might not improve anti-tumor CD4+ T cell responses." (PMID 33859645, 2021). "Nevertheless, one hypothesis that may explain the oncogenic function of KDM6B in T-ALL, versus the tumor suppressive function of KDM6A in T-ALL, could be the lack of N-terminal TPR domain in KDM6B, but the exact cause and mechanism is yet to be explored." (PMID 33003334, 2020). "Previous studies have shown that CXCR4 promotes tumor cell proliferation and migration, mostly through its downstream ERK1/2 and AKT pathways, and therefore, we examined whether the dysregulation of KDM6B expression affects the ERK and AKT pathways in GC cells." (PMID 36564369, 2022). "The knockdown of KDM6B in PDAC cell lines accelerates tumor growth regardless of KRAS status, despite KDM6B being a downstream target of KRAS." (PMID 38791111, 2024). "Moreover, KDM6B, but not KDM6A, regulates RAS/RAF-mediated oncogene-induced senescence (OIS), one of several cell-intrinsic tumor-suppressor responses that function to eliminate aberrantly proliferating, potentially premalignant cells." (PMID 28968467, 2017).
cancer (110 papers, 2012 to 2025). A tumor composed of atypical neoplastic, often pleomorphic cells that invade other tissues. "In contrast to the dual role of KDM6A in cancer, KDM6B has been consistently associated with cancer progression." (PMID 41085408, 2025). "Taken together, growing evidence shows that Kdm6b is associated with many human diseases, for example, developmental diseases, cancer, immune systematic diseases, infection, and urinary systems disorders." (PMID 34716527, 2023). "We divided the cases into high and low KDM6B expressing groups and analyzed the association between the KDM6B expression level and clinical outcomes in different cancer cases." (PMID 35783266, 2022). "Although the role and mechanisms of KDM6B have been studied in various cancers, its function and the associated mechanism in gastric carcinogenesis and progression, are still not fully elucidated." (PMID 36564369, 2022). "As an H3K27me3 demethylase and counteracts polycomb-mediated transcription repression, KDM6B has been implicated in the development and malignant progression in various types of cancers." (PMID 34001062, 2021). "Lately, some studies have also shown that KDM6B is implicated in the pathogenesis of several cancers in a context-dependent fashion; however, to date, the biological function of KDM6B in ESCC remains to be determined." (PMID 34001062, 2021). "Both EZH2 and KDM6B, two proteins with opposite catalytic activities, have previously been associated with cancer aggressiveness or EMT." (PMID 33291363, 2020). "The disparate effects caused by LOF of either KDM6A or KDM6B indicate a complex relationship between the molecular biology of H3K27me3 removal and the cellular biology of cancer development." (PMID 33003334, 2020). "Considering the strong associations between EZH2, KDM6A, KDM6B and development, the link between these proteins and cancer cell plasticity will continue to become more apparent." (PMID 33003334, 2020). "Concurrent action of both KDM6A and KDM6B is frequently associated with cell cycle in differentiated or cancer stem cells." (PMID 33003334, 2020). "Two other genes, ZNF417 and KDM6B, have been associated as part of a gene signature with cancer aggressiveness." (PMID 31323891, 2019). "The H3K27 demethylases KDM6A and KDM6B have also been implicated in carcinogenesis and the finding that KDM6B is the major mediator of OIS further supports the involvement of these enzymes in cancer formation." (PMID 23673719, 2013). "Moreover, we investigated the associations between changes in the KDM6B gene and clinical outcomes in different cancers." (PMID 35783266, 2022). "We found a positive association between KDM6B and HIF1α in various cancer types." (PMID 35186918, 2022). "Furthermore, KDM6B was associated with aggressiveness and enhanced migratory properties of various cancer types." (PMID 35186918, 2022). "We also explored the potential KDM6B-associated pathways in the pathogenesis or clinical outcomes in numerous cancers, including expression difference, survival conditions, genetic changes, DNA methylation, immune infiltration, and related biological processes." (PMID 35783266, 2022). "This is likely because the overexpression of YTHDF2 decreased the mRNA stability of KDM6B in cancer cells." (PMID 39800682, 2025). "For instance, lysine demethylase 6B (KDM6B), an enzyme responsible for histone demethylation, can support a pro-inflammatory response, potentially enhancing the effectiveness of anti-cancer therapies." (PMID 40005571, 2025). "Deregulation of the H3K27me3 balance that is governed by the coordinated enzymatic activities of EZH2 and KDM6A/KDM6B leads to differentiation defects and cancer." (PMID 41085408, 2025). "KDM6B is responsible for colony formation ability while KDM4C increases cancer aggressiveness, respectively." (PMID 40159638, 2025).
cancer (continued). "Our data indicate that METTL3 controls SLC7A11 transcription through GATA binding protein 3 (GATA3) and H3K27 lysine demethylase 6B (KDM6B), highlighting a potential approach for cancer therapy by disrupting m6A-regulated ferroptosis in cancer cells." (PMID 39800682, 2025). "For instance, KDM6B has been shown to inhibit breast cancer metastasis by regulating the Wnt/β-catenin signaling pathway, while promoting metastasis in other cancers such as esophageal squamous cell carcinoma and osteosarcoma." (PMID 40872531, 2025). "We therefore evaluated the expression of KDM6A and KDM6B demethylases in a panel of cancer cell lines." (PMID 41085408, 2025). "KDM6B, which can perform the dual effects of cancer promotion or suppressor base on different cell environment, is a histone demethylase specific for H3K27me356." (PMID 38951569, 2024). "KDM6B is a crucial histone demethylase involved in various biological and pathological processes, including development, inflammation, aging, and cancer." (PMID 39620228, 2024). "KDMs such as KDM1B and KDM6B has been reported to be able to promote cancer cell immune evasion, making them a potential therapeutic target." (PMID 38225241, 2024). "KDM6B is overexpressed in an array of cancers including lung, liver carcinoma, several hematological malignancies, and in primary Hodgkin’s lymphoma." (PMID 36975603, 2023). "The results revealed that the KDM6B expression level was positively related to DNA methyltransferases in various cancers significantly, especially in BRCA−Basa, BRCA−Her2, BRCA−LumA, CESC, DLBC, ESCA, KIRP, LGG, LIHC, and THYM." (PMID 35783266, 2022). "Above all, the results showed that the KDM6B expression had a different impact on the prognosis among various cancers." (PMID 35783266, 2022). "KDM6B regulates a wide range of pathways involved in development, inflammation, and specifically cancers, such as WNT, NF-κB, and BMP." (PMID 35783266, 2022). "KDM6B expression was associated with TMB, MSI, and immune cell infiltration, particularly cancer-associated fibroblasts." (PMID 35783266, 2022). "Treatment of cancer cells with a KDM6B inhibitor downregulated FUT1 (Fucosyltransferase 1) gene, which is also related to metastasis." (PMID 36233212, 2022). "Our study offered a relatively comprehensive understanding of KDM6B’s dual role in cancer development and response to immunotherapy." (PMID 35783266, 2022). "These biological pathways tend to impact response reactions against intracellular or extracellular stimulations and suggest a functional link between KDM6B and clinical diseases, including inflammations, especially, cancers." (PMID 35783266, 2022). "The KDM6B expression level was associated with TMB, MSI, and immune cell infiltration, particularly cancer-associated fibroblasts, across various cancer types with different correlations." (PMID 35783266, 2022). "A pan-cancer study of KDM6B using the TCGA project and the GEO database was conducted here for the first time." (PMID 35783266, 2022). "Over-expression of KDM6B results in unhindered transcription and disrupts core gene-regulatory architecture by decreasing the H3K27me3 level, which plays a dual role in cancers." (PMID 35783266, 2022). "In this article, we reviewed the experimentally determined evidence for the correlation between KDM6B and different cancer types or stages." (PMID 35783266, 2022). "Nonetheless, the role of KDM6B in these cancers, especially KIRC, still needed to be further explored." (PMID 35783266, 2022). "JIB-04 interfered with the cell cycle progression of HCC cells and cancer stem-like cell properties via the AKT2-FOXO3a-RB axis by inhibiting the histone demethylase activity of KDM6B on the AKT2 promoter." (PMID 35887001, 2022).